CXCL10 (C-X-C motif chemokine ligand 10)
Diseases named in the same sentence as CXCL10 in open-access papers (continued):
Sharing a sentence is not in itself a finding about the gene and the disease.
infectious disease (62 papers, 2007 to 2025). A disorder directly resulting from the presence and activity of a microbial, viral, or parasitic agent in humans. "Remarkably, the heightened CCR5, HLA-DR and CXCL-10 expressions are implicated in infectious disease pathogenesis, including HIV, thereby revealing the possibility of OTA to promote HIV mortality and morbidity in infants." (PMID 40423338, 2025). "The alteration of CXCL10 levels is generally linked with infectious disease and is currently emerging as a potential biomarker for several diseases, but a label-free detection of such a small protein with a molecular weight of 10 kDa is challenging." (PMID 38638165, 2024). "Cxcl10 was also up-regulated in other top-ranked infectious diseases including those caused by Adenovirus, Influenza virus, and Orthopoxvirus." (PMID 38107402, 2023). "The activation of CXCL10/CXCR3 is linked to many infectious diseases." (PMID 35604176, 2022). "Although FasL production is highly regulated due to its cytotoxicity, it appears that its plasma levels increase significantly with the severity of this infectious disease in correlation with the C-X-C motif chemokine ligand 10 (CXCL10) production." (PMID 38549864, 2024). "Through binding to its receptor CXCR3, CXCL10 mediates the recruitment and activation of monocytes, T cells and natural killer cells, and therefore plays critical roles in defense against infectious diseases." (PMID 30620752, 2019). "When analyzing plasma samples from patients suffering from infectious diseases, we found that the increase of CXCL10 in these samples correlated well with the severity state of the disease." (PMID 26646682, 2015). "CXCL10 is one of these cytokines and is found to be involved in the pathogenesis of many virus infectious diseases." (PMID 24701034, 2014). "CXCL10 displays neurotoxic effects in various infectious diseases, including mediating demyelination during JHMV infection and inducing neuronal apoptosis during chronic, HIV-1 associated neurological disorders." (PMID 24802239, 2014). "JAK-STAT, TRAF2/TAK1, and PI3K/AKT signaling pathways are reported to be involved in the regulation of CXCL10 in such virus infectious diseases as HIV, HBV, and influenza A." (PMID 24701034, 2014). "Accumulating data have indicated that CXCL10 plays an important role in many virus infectious diseases infected with Hepatitis Virus B (HBV), Hepatitis Virus C (HCV), HIV, influenza virus, and some other viruses." (PMID 24701034, 2014). "The elevated level of CXCL10 has been found to be correlated with the development and the severity of these infectious diseases." (PMID 24701034, 2014). "CXCL10 is known to be a mainly pro-inflammatory chemokine which has, among other functions, an impact in pathogenesis of chronic inflammatory in miscellaneous infectious diseases." (PMID 31575964, 2019). "The vital role of CXCL10 in the pathogenesis has been reported in many virus infectious diseases." (PMID 24701034, 2014). "A better understanding of the regulation mechanism of CXCL10 production in infectious diseases might help us develop new therapeutic interventions in human diseases." (PMID 24701034, 2014). "CXCL10 in particular is a biomarker for high viremia and rapid HIV-1 disease progression, as well as immune dysfunction in infectious diseases more broadly." (PMID 39190496, 2024). "Several genes involved in the control of infectious diseases such as the Basic leucine zipper ATF transcription factor 2 (BATF2) and the C-X-C motif chemokine ligand 10 (CXCL10), were upregulated in the PB and ICV gene expression profiles from the animal with diffuse lesions." (PMID 31619718, 2019). "In fact, both CXCL9 rs10336 TT and CXCL10 rs3921 GG genotypes have also been related to higher cellular expression of CXCL9 and CXCL10 in other infectious disease, such as Chagas infection, where they were also related to a higher severity of chronic Chagas cardiomyopathy." (PMID 28755163, 2017).
infectious disease (continued). "Hence, further studies are needed to explore the downstream and upstream signaling pathways regulating chemokines and their receptors ligands, particularly CXCL10 and their receptor ligands CXCR3, with the aim to exploit new methods to control infectious diseases mediated by theses chemokines." (PMID 28018321, 2016).
bacterial infections (42 papers, 2008 to 2026). "IP-10/CXCL10 has been linked to inflammatory processes, including viral and bacterial infectious diseases." (PMID 38116016, 2023). "Impaired CXCL10 expression increases the susceptibility to bacterial infection." (PMID 32753046, 2020). "The upregulation of pro-inflammatory cytokines, including CXCL8, CXCL10, IL-1β, IL-6 and MMP9 was associated with the progression of host bacterial infection." (PMID 40839565, 2025). "Anyway, further research is needed about the regulation of CXCL10 and its signaling pathways as well as its role in bacterial infection." (PMID 23841502, 2013). "Bacterial infection of ductal cells also coincides with the fact that CXCL9, CXCL10, CXCL12, chemokines involved in lymphocyte trafficking, are predominantly expressed in the ductal epithelium adjacent to lymphoid infiltrates in SS." (PMID 32208441, 2020). "Elevated levels of IL-6, IL-8, and Interferon gamma-induced protein 10 (IP-10, also known as CXCL10) were associated with bacterial infections in febrile patients, irrespective of culture positivity, highlighting their potential as robust biomarkers." (PMID 40137168, 2025). "The correlation between serum CXCL10 levels and serum ferritin is in line with the hypothesis that PMR may be induced by bacterial infections." (PMID 39476056, 2024).
cardiovascular disease (36 papers, 2013 to 2025). "In vitro studies of human coronary artery smooth muscle cells (HCASMCs) performed by Chang showed a functional role for plasma-circulating CXCL10 and IL-17 in the development of vascular calcification and revealed its underlying mechanism in cardiovascular disease." (PMID 34835155, 2021). "According to the most recent scientific evidence, CXCL10 is markedly involved in the pathogenesis of cardiovascular diseases." (PMID 34835155, 2021). "The CXCR3 receptor and its related agonist CXCL10 constitute promising drug targets for the therapy of different cardiovascular disorders." (PMID 34835155, 2021). "Another interesting result is the upregulation of the T-cell chemokine and cardiovascular disease biomarker CXCL10 in our HF-diet fed animals." (PMID 31530895, 2019). "CXCL-10 is a small chemokine that functions as a chemoattractant for many immune cells such as lymphocytes and is a possible biomarker in cardiovascular disease." (PMID 31312177, 2019). "The chemokine receptor CXCR3 and its agonist CXCL10 are potential drug targets to treat various cardiovascular diseases." (PMID 27795961, 2016). "Chemokine CXCL10 is elevated in cardiovascular diseases, along with increased cardiac infiltration of proinflammatory Th1 and cytotoxic T cells." (PMID 27795961, 2016). "Recent evidence from us and others has revealed the importance of the CXCL10/CXCR3 axis in cardiovascular diseases." (PMID 27795961, 2016). "This study confirms our previous finding that CXCL10, sCD163 and sCD14 have distinct although overlapping associations with different aspects of HIV infection and treatment, as well as cardiovascular disease risk factors and demographic variables." (PMID 27355513, 2016). "In this review, we summarized the role of CXCL10 in different cardiovascular diseases, in both the experimental and clinical setting." (PMID 24868552, 2014). "The aim of this review is to summarize the role of CXCL10 in cardiovascular disease in both experimental and clinical studies and highlight the discrepancies between the different settings." (PMID 24868552, 2014). "After binding to its receptor CXCR3, CXCL10 evokes a range of inflammatory responses: key features in cardiovascular disease (CVD)." (PMID 24868552, 2014). "In this review, the role of C-X-C motif ligand 10 (CXCL10) in different cardiovascular disease models will be highlighted." (PMID 24868552, 2014). "Table 1provides an overview of the role of CXCL10 in cardiovascular disease in experimental and clinical settings." (PMID 24868552, 2014). "The use of CXCL10 as a biomarker in cardiovascular disease will be discussed further in this review." (PMID 24868552, 2014). "Levels of immune activation markers (T cell immune phenotype, sCD25, sCD14, sCD163), microbial translocation (LPS) and biomarkers of cardiovascular disease and impaired cognitive function (sVCAM-1, sICAM-1 and CXCL10) were evaluated." (PMID 23724003, 2013). "Of note, the CXCL10 level is elevated in cardiovascular disease." (PMID 37019881, 2023). "CXCL10 is involved in different levels of cardiovascular disease severity." (PMID 24868552, 2014). "CXCL10 has been studied extensively in cardiovascular diseases, both experimentally and clinically." (PMID 24868552, 2014). "Similar ligands have been designed that exert CXCL11-like actions following an attachment to CXCR3 but their applications on cardiovascular diseases in experimental rodent models has yet to be elucidated, a fact that may be due to the short in vitro half-life of CXCL10." (PMID 34835155, 2021). "Thus, the finding that HIV acts synergistically with age to increase CXCL10 levels may have implications for the development of cardiovascular disease in HIV positive individuals." (PMID 23365694, 2013).
cardiovascular disease (continued). "In order to establish potential outcomes of abnormal IA, MT and CD4 cell count observed in the HIV+ women, we sought to determine whether they would correlate with biomarkers of cardiovascular disease (sVCAM-1, sICAM-1) and impaired cognitive function (CXCL10)." (PMID 23724003, 2013). "For instance, CCR5 and CXCL10/IP-10 antagonists are currently being validated in clinical trials to treat HIV and cardiovascular diseases, respectively." (PMID 34046036, 2021). "Interestingly, CCL5, CXCL10, and CXCL11 — which have been reported to play a key role in the pathogenesis of cardiovascular disease — appeared to be most upregulated (more than 10-fold)." (PMID 26837541, 2016).
inflammation (28 papers, 2007 to 2025). Aberrant reaction of the microcirculation characterized by movement of fluid and leukocytes from the blood into extravascular tissues. "Among them, those associated with systemic inflammation have been characterized and shown to express high levels of classical pro-inflammatory genes including Il6, Cxcl10, Il1b and Tnf." (PMID 34483912, 2021). "In particular, the serum CXCL9 and CXCL10 levels in our patients showed correlations with BALF levels so that these serum chemokines may reflect not only systemic inflammation but also local pulmonary inflammation." (PMID 33137121, 2020). "By blocking CXCR3 with gene deletion or activating CXCR3 with intravitreal injection of CXCL10, we clearly demonstrate that CXCR3 is involved in retinal inflammation, oxidative, and nitrosative stress, and retinal neuronal death during acute glaucoma." (PMID 26448323, 2015). "Using the LPS-AKI model, we found that administration of nicotinic agonists blunted kidney inflammation (e.g. TNFα, CCL2, and CXCL10)." (PMID 22586448, 2012). "Cervicovaginal inflammation can be measured by increased levels of secreted pro-inflammatory markers including IL-1α, IL-1β, and IL-6 or chemokines including MIP-1α, MIP-1β, and Interferon-γ inducible protein 10 (IP-10) also known as CXCL10." (PMID 36726972, 2022). "However, urinary CXCL10 seems to be associated with tubulointerstitial inflammation and peritubular capillaritis, rather than glomerulitis or isolated vascular inflammation and urinary CXCL10, but not CXCL9, correlates with subclinical rejection (AUC 0.64; 95% CI, 0.55-0.73)." (PMID 37675106, 2023).
neurological diseases (28 papers, 2009 to 2026). "The severe neurological disorders have been associated with specific immune responses such as elevated levels of CXCL‐10 (also termed IP‐10) or Th17 cytokines but further characterization is required." (PMID 41556482, 2026). "Microglia–astrocyte interactions and the upregulation of CXCL10 are common features in various neurological disorders and aging, associated with increased numbers of CD8+CXCR3+ TRM cells." (PMID 40404995, 2025). "One of the TBI-induced genes modulated by IFNAR deficiency, Cxcl10, is well recognized for its involvement in a variety of neurologic diseases." (PMID 37596685, 2023). "CXCL10 is found to be increased in HIV+ patients with HIV-associated neurologic disorders, wherein it is considered to be neurotoxic." (PMID 23724003, 2013). "Taken together, these results support the importance of elevated CXCL10 in MS and other neurological disorders and support an alternative mechanism of CXCL10 outside of immune cell trafficking into the CNS." (PMID 37627269, 2023). "Among the CXC family chemokines, CXCL-10 is the most important in inducing inflammatory response by leukocytes in several diseases of the nervous system." (PMID 34959581, 2021). "The activity of IFN-γ-inducible CXC chemokines mediated via CXCR3 was firstly investigated using a model of DENV-induced neurological disease in wild-type (WT), CXCR3-or CXCL10/IP-10 deficient mice." (PMID 22815692, 2012). "Ligands of the CXCR3 receptor include CXCL9, CXCL10, and CXCL11, exhibit varied roles across different neurological disorders." (PMID 40781073, 2025). "On the contrary, neurological presentations were inversely associated with markers of disease severity such as IL-6, TNF-α, IL-10/CXCL10, CRP, D-dimer, and LDH, all of which were significantly lower in patients with neurological diseases." (PMID 36851766, 2023). "It is associated with activation of astrocytes and microglia with marked production of cytokines, chemokines, proinflammatory mediators including C-X-C motif chemokine ligand 10 (CXCL10), and TGFβ, and BBB disruption in neurological diseases such as CM." (PMID 34692564, 2021). "Based on these findings, CXCL10 has been speculated as a plasma inflammatory biomarker of immune activation in both viremic and aviremic HIV patients on cART therapy and, was found to be associated with a more rapid HIV/SIV neurological disease progression via the influx of CXCR3+ cells in the CNS." (PMID 34527676, 2021). "We compared CSF samples from HAM and HTLV-1-uninfected non-neuroinflammatory neurological disease patients (control group) to establish cut-off values for neopterin and CXCL-10 based on ELISA tests." (PMID 39861878, 2025). "The CXCL-10 biomarker in CSF also proved to be an accurate marker to differentiate a neuroinflammatory reaction by DENV and CHIKV in the nervous system in relation to the group of non-inflammatory neurological diseases." (PMID 34959581, 2021).
immune dysfunction (27 papers, 2006 to 2025). "Both CXCL10 and 11 are pro-inflammatory cytokines positively regulated by IFNγ and their increased activity is associated with different immune disorders." (PMID 37470035, 2023). "The upregulation of NEAT1 has been shown to promote the release of several inflammasomes (NLRP3, NLRC4, and AIM2) and pro-inflammatory cytokines (CXCL10, IL-6, and IL-1β), resulting in an immune response in inflammatory and immune diseases." (PMID 35127819, 2021). "It was further shown that monoclonal antibodies against C-X-C motif chemokine 10 (CXCL-10 or IP-10) or interleukin 17A (IL-17A), used to treat immune system diseases, were able to ameliorate ALI induced by swine-origin influenza A H1N1 in mice." (PMID 32176725, 2020). "Overall, these results suggested that FC-98 was a potential molecule in the treatment of CXCL-10-mediated immune diseases." (PMID 24696007, 2014). "CSF CXCL13, CXCL10, IL-6 and IFN-α are elevated in a number of infectious and immune disorders." (PMID 27575749, 2016). "Besides, CXCL10, CXCL11, and IL-10 also played critical roles in immune disease." (PMID 40458609, 2025). "Some IRPs in cluster 7, such as CXCL11, CXCL9, TNF, CXCL10, and IL18, are closely associated with HIV-1 disease progression and immune disorders, irrespective of whether patients received ART treatment." (PMID 36408648, 2023). "Particularly, CXCL9, CXCL10, and CXCL11 in cluster 7 were closely associated with disease progression and immune disorders, irrespective of whether the patients had been treated with ART." (PMID 36408648, 2023).